C1GALT1 (core 1 synthase, glycoprotein-N-acetylgalactosamine 3-beta-galactosyltransferase 1)
Diseases named in the same sentence as C1GALT1 in open-access papers (continued):
Sharing a sentence is not in itself a finding about the gene and the disease.
breast carcinoma (14 papers, 2011 to 2025). "The association of high C1GalT1 expression with poorer prognosis in breast cancer patients can be further enhanced by the presence of high levels of the polypeptide N-acetyl-galactosaminyltransferase (GALNT) family members GALNT1 or GALNT8." (PMID 34944925, 2021). "The authors determined that C1GALT1 mRNA and protein levels were found to be higher in breast cancer cell lines and associated with a higher histological grade and tumor stage." (PMID 32075174, 2020). "Conversely, overexpression of C1GalT1 in breast cancer cells increased association between MUC1 and β-catenin by promoting the shedding of the extracellular domain, which was correlated with increased migratory and invasive behavior." (PMID 27483328, 2016). "Loss of Core 1 derived glycans through knockout of C1GalT1 in a mouse model of breast cancer was shown to decrease the incidence of tumor development." (PMID 27483328, 2016). "Therefore, it is likely that conformational changes in MUC1 caused by C1GALT1 modification instead of steric hindrance of complex O-glycans play the predominant role in the proteolytic cleavage of MUC1 in breast cancer cells." (PMID 25762620, 2015). "The strongest associations—where C1GALT1 expression correlated with all tested proliferation markers—were found in pancreatic, bladder, and breast cancers, suggesting that C1GALT1 may play a particularly influential role in regulating proliferative capacity in these tumors." (PMID 40548474, 2025). "One study reported that C1GALT1 expression was notably higher in breast cancer tumors with high Ki67 levels compared to those with low Ki67 levels." (PMID 40548474, 2025). "C1GALT1 expression was significantly positively correlated with all proliferation‐related genes in pancreatic, bladder, and breast cancers." (PMID 40548474, 2025). "Breast cancer showed a similar trend, with normal tissues significantly exceeding C1GALT1 gene expression levels compared to tumor tissues (p = 4.876e‐13)." (PMID 40548474, 2025). "Patients with lower C1GalT1 expression were reported to survive 20% better over a 100-month period than those with higher C1GalT1 expression in breast cancer." (PMID 34944925, 2021). "Overexpression of C1GalT1 by transfection in breast cancer MCF-7 cells increased the interaction of the MUC1 C-terminal with β-catenin, causing increased cancer cell migration and invasion in vitro and increased tumor growth in mice." (PMID 34944925, 2021). "We previously indicated that C1GALT1 knockdown suppresses the MUC1-C/β-catenin signaling pathway in breast cancer cells." (PMID 32005975, 2020). "In another study highlighting the role of C1GALT1, the authors used an animal model to identify the in vivo role of C1GALT1 in breast cancer." (PMID 32075174, 2020). "Another example is C1GalT1, an enzyme overexpressed in breast carcinoma that correlates with higher histological grade and advanced tumor stage." (PMID 27754373, 2016). "Here, we demonstrate that C1GALT1 expression regulates O-glycans on MUC1-N and promotes MUC1-C association with β-catenin and nuclear translocation in breast cancer cells." (PMID 25762620, 2015). "Consistently, immunohistochemical staining of C1GALT1 in a breast cancer tissue microarray shows that C1GALT1 protein is frequently overexpressed in breast cancer tissues compared with normal tissues." (PMID 25762620, 2015). "C1GALT1 mRNA and protein expression levels in breast cancer cell lines, including MCF-10A, MCF-7, T47D, MDA-MB-435, SKBR3, and MDA-MB-231, were analyzed by Q-RT-PCR and Western blotting, respectively." (PMID 25762620, 2015). "Here, we report that C1GALT1 is overexpressed in breast cancer and its overexpression enhances malignant growth of breast cancer cells through modifying MUC1 O-glycosylation and signaling." (PMID 25762620, 2015).
breast carcinoma (continued). "Public databases and our data showed that C1GALT1 mRNA and C1GALT1 protein are frequently up-regulated in breast cancer; and increased C1GALT1 expression correlates with higher histological grade and advanced tumor stage." (PMID 25762620, 2015). "Unveiling the function of C1GALT1 in breast cancer opens new insights to the roles of C1GALT1 and O-glycosylation in tumorigenesis and renders the potential of C1GALT1 as a target of novel therapeutic agent development." (PMID 25762620, 2015). "This study aims to determine the correlation between C1GALT1 expression and breast cancer clinicopathological features and roles of C1GALT1 in breast cancer malignant phenotypes." (PMID 25762620, 2015). "Overexpression of C1GALT1 enhanced breast cancer cell growth, migration, and invasion in vitro as well as tumor growth in vivo." (PMID 25762620, 2015). "This study provides a new insight into the function of C1GALT1 in regulating O-glycosylation and malignant phenotypes of breast cancer and suggests C1GALT1 as a target of therapeutic drug development." (PMID 25762620, 2015). "C1GALT1 expression levels are also up-regulated across a selection of 9 breast cancer biosets (NextBio Research)." (PMID 25762620, 2015). "Although C1GALT1 plays critical roles in many pathophysiological functions, the expression and function of C1GALT1 in breast cancer are still unclear." (PMID 25762620, 2015). "However, another study reported varying correlations between Ki‐67 levels and C1GalT1 expression across different breast cancer cell types in knockout experiments." (PMID 40548474, 2025). "Our analysis was transcriptomic analysis, and all breast cancer subtypes were grouped together for statistical evaluation, which might have obscured subtype‐specific variations in C1GALT1 expression." (PMID 40548474, 2025). "Rømer reported that the glycosylation was induced by changing the levels of ZIP9 and Zn2+.C1GALT1, a key regulated enzyme of O-glycosylation, plays an important role in the cancer development, metastasis and prognosis, such as breast cancer, bladder cancer, neuroblastoma and endometrial cancer." (PMID 38845937, 2024). "However, many investigators have reported higher expressions of C1GALT1 in breast cancer progression." (PMID 32075174, 2020). "C1GalT1 also promotes breast cancer cell growth, migration, and invasion." (PMID 27754373, 2016). "Little is known about the function of C1GALT1 in breast cancer." (PMID 25762620, 2015). "We also demonstrate that inhibiting C1GALT1 is sufficient to suppress tumor growth in vitro and in vivo, suggesting that C1GALT1 may serve as a therapeutic target for breast cancer treatment." (PMID 25762620, 2015). "To investigate whether C1GALT1 expression can modify O-glycan expression on breast cancer cell surfaces, we performed flow cytometry with Vicia villosa agglutinin (VVA) lectin, which is specific for GalNAc (Tn antigen) binding." (PMID 25762620, 2015). "Interestingly, we found that C1GALT1 knockdown decreases MUC1-N shedding, whereas C1GALT1 overexpression enhances MUC1-N shedding in breast cancer cells." (PMID 25762620, 2015). "In vitro and in vivo results show that up-regulation of C1GALT1 promotes breast cancer cell growth." (PMID 25762620, 2015). "However, in only 3 out of 58 breast carcinoma samples was a β3GNT6 transcript detectable and these were at least 100-fold lower than the glycosyltransferase, C1GALT1, that competes for the same sugar substrate to form core 1 (T)." (PMID 21385452, 2011). "We found that the β3GNT6 transcript could only be detected in 3 of 58 breast carcinomas, and even then the level was at least 100-fold lower than the competing glycosyltransferase, C1GALT1." (PMID 21385452, 2011). "Similarly, both in vivo and in vitro studies demonstrated that hepatocellular carcinoma cells lacking C1GalT1 exhibited reduced Ki‐67 staining compared to wild‐type, and breast cancer tissues in C1GalT1‐deficient mice showed fewer Ki67‐positive cells." (PMID 40548474, 2025).
breast carcinoma (continued). "Thus, this study was the first report to determine the prognostic role of C1GALT1 in breast cancer." (PMID 32075174, 2020). "Next, we investigated whether C1GALT1 affects O-glycosylation in breast cancer cells." (PMID 25762620, 2015). "With respect to the O-GalNAc pathway, we observed alterations in several related glycogenes including the downregulation of GCNT4, GALNT13, GALNT16 and C1GALT1, and upregulation of ST3GAL1, ST6GALNAC4 and GAL3ST2 in Her2+ breast cancer tissue." (PMID 36282863, 2022). "The mechanistic investigation indicates that C1GALT1 regulates the O-glycan structures on MUC1 oncoprotein, and promotes MUC1-N shedding and MUC1-C/β-catenin signaling pathway in breast cancer cells." (PMID 25762620, 2015). "In this study, we found that overexpression of C1GALT1 decreases Tn antigens and increases T antigens on cell surfaces and MUC1 and enhances breast cancer cell malignant behaviors." (PMID 25762620, 2015). "Here, we report that C1GALT1 is a critical regulator for O-glycan structures on MUC1-N and C1GALT1 promotes breast cancer progression through MUC1 shedding and MUC1-C/β-catenin signaling pathways." (PMID 25762620, 2015). "Furthermore, C1GALT1 modulates O-glycan structures on Mucin (MUC) 1 and promotes MUC1-C/β-catenin signaling in breast cancer cells." (PMID 25762620, 2015). "We therefore hypothesize that C1GALT1 can modify MUC1 O-glycosylation, affect MUC1 signaling, and in turn regulate breast cancer cell behaviors." (PMID 25762620, 2015).
colon cancer (12 papers, 2013 to 2025). "A study has observed that mice with C1galt1-deficient intestinal epithelial cells inducing colitis grow up to develop colon tumors." (PMID 39767078, 2024). "In this study, suppression of C1GalT1 expression in human colon cancer cells is shown to cause significant reduction of tumour cell proliferation, migration, adhesion and colony formation." (PMID 37612278, 2023). "Similarly, a recent study elucidated that suppression of C1GALT1 caused the changing of protein glycosylation and the reducing cell adhesion and migration in colon cancer cells." (PMID 38845937, 2024). "This study reports that suppression of C1GalT1 expression in human colon cancer cells caused substantial changes of protein glycosylation of cell membrane proteins, many of which were ligands of the galactoside-binding galectin-3 and the macrophage galactose-type lectin (MGL)." (PMID 37612278, 2023). "Strong expression of C1GALT1, which encodes an enzyme required for the initial step of protein O-glycosylation, has been reported to predict poor prognosis of head and neck cancer, hepatocellular carcinoma, colon cancer, and ovarian cancer, possibly by regulating growth factor signaling." (PMID 38622340, 2024). "Colon cancer followed a similar trend, showing lower C1GALT1 levels in normal tissues compared to tumor tissues (p = 2.487e‐18)." (PMID 40548474, 2025). "C1GALT1, a key player in colon cancer pathogenesis, significantly influences the behavior and properties of cancer cells." (PMID 38699634, 2024). "This further underscores C1GALT1’s significant role in the progression and characteristics of epithelial cancers, including colon cancer." (PMID 38699634, 2024). "In mice models lacking intestinal epithelial core 1 O-glycans (IEC C1GALT1−/− mice) or gastric epithelial O-glycans (GEC C1galt1−/− mice), spontaneous colitis and gastritis, as well as gastric or colon tumors, were developed, respectively." (PMID 38662050, 2024). "This study demonstrated that change of C1GalT1 expression by shRNA in colon cancer cells substantially alters the O-glycosylation profile of cellular proteins." (PMID 37612278, 2023). "Overexpression of C1GalT1 in colon cancer cells changed the O-glycan structures of FGFR2, which enhanced FGFR2 interaction with bFGF- and bFGF-mediated malignant phenotypes." (PMID 34944925, 2021). "To investigate the effect of C1GALT1 on tumor growth in vivo, we performed subcutaneous injection of colon cancer cells in NOD/SCID mice." (PMID 24758762, 2014). "To investigate roles of C1GLAT1 in colon cancer cells, we first analyzed C1GALT1 expression in six colon cancer cell lines Caco2, HT29, Colo205, SW480, SW620, and HCT116 by Western blotting." (PMID 24758762, 2014). "To investigate effects of C1GALT1 on malignant phenotypes, we analyzed cell viability, migration and invasion in colon cancer cells." (PMID 24758762, 2014). "The stable overexpression and shRNA-mediated knockdown of C1GALT1 in colon cancer cells were confirmed by Western blotting." (PMID 24758762, 2014). "Collectively, these results indicate that bFGF signaling pathways are involved in cancer stemness and malignant phenotypes induced by C1GALT1 in colon cancer cells." (PMID 24758762, 2014). "C1GALT1 overexpression promoted cell survival, migration, invasion, and sphere formation as well as tumor growth and metastasis of colon cancer cells." (PMID 24758762, 2014). "C1GALT1 overexpression enhances the invasive potential and stem-like cell property of colon cancer cells via modifying O-glycosylation and activity of FGFR2." (PMID 24758762, 2014). "We next investigated the mechanisms by which C1GALT1 regulates malignant phenotypes of colon cancer cells." (PMID 24758762, 2014).
colon cancer (continued). "A study on colon cancer cells found that the expression of silyl-Tn was associated with an increase in the α2,6-carbamoyltransferase gene (ST6GALNAC1) and a decrease in the core 1 synthase gene (C1GALT1) in LS174T cells, by qRT-PCR." (PMID 38699634, 2024). "For instance, C1GALT1 expression was reported to be required for fibroblast growth factor receptor phosphorylation through O-glycosylation in colon cancer tissue and for binding of epidermal growth factor to its receptor (EGFR) through EGFR O-glycosylation in head and neck cancer." (PMID 38622340, 2024). "A series of analyses were conducted in this study and showed that alteration of C1GalT1 expression in human colon cancer cells reciprocally changes tumour cell-cell and tumour-macrophage interactions mediated by galectin-3 and MGL with significant impact on tumour growth and progression." (PMID 37612278, 2023). "C1GALT1 was expressed in colon cancer cells at different levels." (PMID 24758762, 2014). "Moreover, transient knockdown of C1GALT1 with two different siRNAs confirmed the role of C1GALT1 in migration and invasion of colon cancer cells." (PMID 24758762, 2014). "Since cancer stem cells play a critical role in malignant diseases, we therefore investigated whether C1GALT1 is able to modulate the stem-like properties in colon cancer cells." (PMID 24758762, 2014). "Furthermore, BGJ398 significantly blocked the effects of C1GALT1 on the malignant behavior of colon cancer cells." (PMID 24758762, 2014). "Therefore, the overexpression of C1GALT1, leading to a reduction in the quantity or activity of core 3 synthase and subsequent decrease in the core 3 structure, may contribute to the development of colon cancer." (PMID 38699634, 2024). "The competition between these three enzymes was tested by selective suppression of C1GALT1, resulting in increased expressions of sialyl-Tn and GSL-II binding (Core-3 glycans) in human colon cancer cells." (PMID 35207462, 2022). "Transfection of human colon cancer HCT116 and SW480 cells with C1GalT1 reduced the binding of Tn-binding lectin VVA to FGFR2 while knockdown C1GalT1 increased VVA binding to FGFR2 (indications of increased and reduced FGFR2 O-glycosylation, respectively) in the cells." (PMID 34944925, 2021). "Although C1GALT1 controls many cellular behaviors and EGFR serves as a therapeutic target in several malignancies, including HNSCC, lung cancers, and colon cancers, the therapeutic potential of targeting C1GALT1 and its effect on EGFR signaling in HNSCC remain unclear." (PMID 29930379, 2018).
hepatocellular carcinoma (12 papers, 2014 to 2025). A malignant tumor that arises from hepatocytes. "Furthermore, an in vivo study using cell lines and mouse models revealed that overexpression of C1GALT1 in hepatocellular carcinoma tissues was linked to advanced tumor stages, metastasis, and poor prognosis, findings that are parallel to those in our study." (PMID 40548474, 2025). "C1GalT1 overexpression in hepatocellular cancer HCC36 cells by transfection increased TF occurrence on integrin-β1, whereas knockdown of C1GalT1 by shRNA in HA22T hepatocellular cancer cells suppressed the TF expression on integrin-β1." (PMID 34944925, 2021). "Recent studies have shown that C1GalT1 is overexpressed in many common cancers including colon, breast, gastric, lung, head and neck, pancreatic, esophageal, prostate, and hepatocellular cancer." (PMID 34944925, 2021). "Recent studies have shown that C1GalT1 is overexpressed in many cancers of epithelial origin including colon, breast, gastric, head and neck, pancreatic, esophageal, prostate, and hepatocellular cancer." (PMID 34944925, 2021). "In hepatocellular cancer, patients with low C1GalT1 expression had a doubled survival rate compared to those with high C1GalT expression over 60 months." (PMID 34944925, 2021). "Mice injected with C1GalT1-overexpressing hepatocellular cancer cells produced more metastasis nudes on the animal lungs in comparison to mice injected by C1GalT1 knockdown cells." (PMID 34944925, 2021). "Overexpression of C1GalT1 in hepatocellular cancer cells increased the occurrence of TF and STn structures on integrin-β1 and increased integrin activation and FAK signaling, leading to increased cell adhesion, migration, and invasion." (PMID 34944925, 2021). "C1GALT1 modified the O-glycosylation of MET in hepatocellular carcinoma." (PMID 34452648, 2021). "Significantly higher C1GalT1 expression at protein or mRNA levels is seen in lung, colon, breast, gastric, head and neck, pancreatic, esophageal, prostate, ovarian, and hepatocellular cancers." (PMID 34944925, 2021). "For instance, overexpression of core 1 β1,3-galactosyltransferase (C1GALT1) modifying the core 1 O-glycans on β1 integrin increased cell adhesion to ECM coinciding with an advanced tumor stage and poor survival in hepatocellular carcinoma." (PMID 34646995, 2021). "Additionally, C1GALT1 has been shown to modify O‐glycosylation of receptor tyrosine kinases, such as MET with the enhancement of HGF‐induced activation in hepatocellular carcinoma." (PMID 39844613, 2025). "Enhanced C1GalT1 expression by transfection reduced the occurrence of Tn antigen on RTK member MET and inhibited HGF-induced MET activation and viability of HA22T and PLC5 hepatocellular cancer cells." (PMID 34944925, 2021). "It has been documented that the elevated expression of C1GALT1 contributes to the increased O-glycosylation of Mucin-1 (MUC1) in patients with esophageal squamous cell carcinoma and enhances the invasive and metastatic phenotype by modifying O-glycans on integrin β1 in hepatocellular carcinoma." (PMID 38254730, 2024).